RNU6-1217P (RNA, U6 small nuclear 1217, pseudogene)
Gene: Small nuclear RNA gene on chromosome 4 (119,434,005 to 119,434,108, reverse strand). Ensembl gene ENSG00000223208.
Homologues: Orthologues: chimpanzee U6 (100% identical), macaque U6 (91% identical), pig U6 (84% identical), pig U6 (78% identical), dog U6 (77% identical). Paralogues in human: RNU6-1076P (100% identical), RNU6-1100P (100% identical), RNU6-1118P (100% identical), RNU6-355P (100% identical), RNU6-447P (100% identical), RNU6-785P (100% identical), RNU6-791P (100% identical), RNU6-860P (100% identical), U6 (100% identical), RNU6-1054P (99% identical), RNU6-1199P (99% identical), RNU6-1319P (99% identical), and 1289 more.